KRAS (KRas proto-oncogene, GTPase)
Diseases named in the same sentence as KRAS in open-access papers (continued):
Sharing a sentence is not in itself a finding about the gene and the disease.
tumor (continued). "Mutant KRAS has been detected in circulating tumor DNA (ctDNA) at all stages of PDAC using analysis methods such as next-generation sequencing (NGS)." (PMID 42158852, 2026). "CRC with wild-type KRAS/BRAF, microsatellite stability, and low tumor mutational burden is generally considered to have a low risk of central nervous system (CNS) dissemination." (PMID 42109661, 2026). "These organoids showed a loss of differentiation markers in alveolar type 2 cells upon KRAS activation, mimicking both mouse models and human tumor samples." (PMID 41511364, 2026). "At this stage, we know little about the dual role of SMARCA4 as both a tumor suppressor and context-dependent oncogene in KRAS-driven cancers." (PMID 41541668, 2026). "As CRC cells progressed, as indicated by KRAS expression, the expression of tumor acidosis markers (LAMP2, GLUT1, and LDHA), as well as dysadherin, also increased." (PMID 41535258, 2026). "This distribution reflected a major contribution from Arg1450 truncations, which were strongly associated with KRAS-activating mutations, occurring in 168 out of 509 (33%) KRAS-mutant tumours compared with in 51 out of 443 (11.5%) KRAS WT tumours." (PMID 41339549, 2026). "Through systematic pharmacological screening, we identified a novel acridine derivative, LS-1-2, that effectively suppresses KRAS-driven tumor growth and metastasis." (PMID 41362735, 2026). "Among the oncogenic drivers, KRAS mutations stand out for their role in orchestrating immune suppression and PDAC tumor maintenance." (PMID 41550359, 2026). "The TME plays a major role in tumor progression, metastasis, and resistance to conventional therapies through a network of dysregulated signaling pathways, including KRAS, PI3K/AKT/mTOR, Raf/MAPK/ERK, TGF-β, NF-κB, Notch and Hedgehog." (PMID 42294061, 2026). "Here, we report a rare case of a KRAS G12D‐mutated PPC penetrating the visceral pleura, leading to rapid tumour growth and uncontrolled hemothorax." (PMID 41503246, 2026). "Disrupting the KRAS-PDEδ interaction disrupts KRAS trafficking and distribution, interfering with the KRAS signaling pathway and effectively inhibiting tumor cell proliferation." (PMID 41497405, 2026). "Together, these data demonstrate that afatinib and tozasertib cooperate to engage both apoptotic and cell cycle regulatory programs, resulting in enhanced anti-tumor activity in KRAS mutant LUAD." (PMID 41526435, 2026). "RAS-targeted PROTACs are also underway, with ACBI3 degrading most of the common KRAS mutants and inducing tumor regression in vivo." (PMID 41272322, 2026). "A comprehensive assessment of the post-treatment tumor microenvironment revealed that KRAS degradation increased tumor-derived CCL5 levels, thereby promoting CD8+ T-cell recruitment and amplifying antitumor responses." (PMID 41944287, 2026). "Spatial transcriptomics validated the co-localization of USP54 expression, elevated DUB activity, and KRAS signaling within specific tumor niches adjacent to THBS1-enriched immune regions." (PMID 41929495, 2026). "Although single-agent KRAS G12C inhibitors have demonstrated clinical activity in other tumor types and are increasingly considered off-label in selected patients with KRAS p.G12C-mutant BTC their efficacy as monotherapy remains limited." (PMID 41535645, 2026). "RAF1 is essential for KRAS-driven tumor maintenance through kinase-independent survival functions, making it an attractive candidate for targeted protein degradation." (PMID 41650121, 2026).
tumor (continued). "In an HCT-8 (KRAS G13D) xenograft model, PrPC monotherapy inhibited tumor growth in a dose-dependent manner, and 5-fluorouracil (5-FU) monotherapy produced an intermediate effect." (PMID 41683587, 2026). "We next assessed two additional blood‐based markers, pre‐surgery circulating tumour DNA‐based KRAS mutation detection (ctKRAS) and CA19‐9, as well as primary tumour volume as measured from pre‐surgery imaging." (PMID 41549760, 2026). "BBO-8520 exerted more potent and sustained inhibition of KRAS G12C and anti-tumor activity in vitro and in vivo compared with sotorasib, a KRAS G12C (OFF)-only inhibitor." (PMID 42094443, 2026). "The emergence of a KRAS mutation in the metastatic site explained resistance to anti-EGFR therapy and highlighted the importance of reassessing tumor genetics during disease progression." (PMID 42130526, 2026). "Together, these findings support a model in which KRAS-targeted therapy functions not only as tumoricidal therapy but also as immune conditioning of the tumor microenvironment." (PMID 42226008, 2026). "Here, we developed a preclinical LUAD mouse model and demonstrated that targeted oncogenic KRAS degradation induces rapid tumor regression primarily due to cancer cell-autonomous mechanisms." (PMID 42200804, 2026). "Under this metabolic stress, SW48+/G12D and SW48+/G12V cells notably exhibited increased resilience and enhanced viability in low glucose/high glutamine environments, a condition reported, for example, in some KRAS-driven tumour models." (PMID 41266617, 2026). "Regressive mutations in KRAS and SMAD4, as well as specific ERBB2 point mutations, have been shown to influence tumor growth kinetics, metastatic behavior, and responsiveness to targeted or cytotoxic agents." (PMID 41492104, 2026). "The oncogene KRAS drives tumor growth by activating pathways such as MAPK and PI3K-AKT in a constitutive manner." (PMID 41597264, 2026). "Collectively, our data show that DKK3 acts cell‐autonomously to preserve acinar integrity in a KRAS wild‐type context and exerts a tumor‐suppressive role during KRASG12D‐driven PDAC progression." (PMID 41147409, 2026). "STK11 mutations frequently co-occur with KRAS and KEAP1 alterations, exhibit low PD-L1 expression, an immunosuppressive tumor microenvironment that leads to the development of PD-1/PD-L1 resistance." (PMID 42187558, 2026). "Our findings demonstrate that RBM47- and PTBP1-mediated alternative splicing of KRAS contributes to enhanced tumor progression, highlighting KRAS alternative splicing as a promising therapeutic target for cancer treatment." (PMID 41368203, 2026). "11/12 and 10/12 patients generate a significant increase in average T cell response to 6 mutant KRAS antigens and tumor-specific response, respectively." (PMID 41667470, 2026). "We report the development and characterization of high-affinity anti-PCDH7 monoclonal antibodies (mAbs) that inhibit downstream mitogen-activated protein kinase (MAPK) pathway activation and suppress tumor growth in multiple mutant KRAS-driven models." (PMID 42234744, 2026). "Taken together, our data suggest that NPM1 is required for WNT-driven intestinal cell proliferation and tumor initiation; this dependency persists after oncogenic KRAS activation, which drives resistance to epidermal growth factor receptor and mTOR inhibition." (PMID 41413654, 2026). "By inhibiting prenylation, statins disrupt KRAS function, impeding its role in promoting tumor growth." (PMID 41511990, 2026). "KRAS, NRAS, BRAF, and PIK3CA mutations occur at different frequencies in CRC and exert distinct effects on tumor biology, including the composition and functional properties of the TME, particularly its immune component." (PMID 41596586, 2026).
tumor (continued). "Third, we identified context-dependent epistatic KRAS-tumour suppressor interactions and show that reciprocal dosage sensitivities dictate the entity-specific patterns of cancer gene alterations, explaining their frequency, zygosity and acquisition chronology." (PMID 41741657, 2026). "This is supported by preclinical evidence of us and others showing that KRAS mutant LUADs require tonic input from activated ERBB family members for tumor initiation and progression." (PMID 41526435, 2026). "Activation of the ERK cascade by mutant KRAS promotes tumor progression by enhancing cell proliferation, epithelial-to-mesenchymal transition, and resistance to apoptosis." (PMID 41368203, 2026). "We report a rare case of KRAS G12D positive pulmonary pleomorphic carcinoma penetrating the visceral pleura, leading to rapid tumour growth and uncontrolled hemothorax." (PMID 41503246, 2026). "Another study indicated that SLC7A5 maintains intracellular amino acid levels through transcriptional and metabolic reprogramming following KRAS activation, further supporting the demand of the tumor cells for extensive protein synthesis." (PMID 41362725, 2026). "This ANGPTL4‐dependent proinflammatory SASP can promote human neutrophil activation in ex vivo assays, or tumor initiation in a KRAS‐dependent lung tumorigenesis model in mice." (PMID 41347893, 2026). "While outside the scope of this study, other NFAT family members, such as NFAT5, have been implicated in KRAS inhibitor resistance through roles in EMT and tumor plasticity." (PMID 40856537, 2026). "In KRAS-driven tumor cells, NOX4 activity enables cells to adapt to oxidative stress, thereby promoting tumor progression." (PMID 41328353, 2026). "Despite initial tumor cell depletion, the emergence of treatment-insensitive KRAS-mutant clones motivated the refinement of the technique by using base editing in cancer." (PMID 41272322, 2026). "The primary objective for the Phase 1b dose expansion (n = 83) was to evaluate the safety and tolerability of olomorasib in specific KRAS G12C-mutant tumor types." (PMID 41820335, 2026). "Collectively, our findings highlight the critical role of alternative splicing in modulating wild-type KRAS function and its contribution to tumor progression." (PMID 41368203, 2026). "In tumors with KRAS mutations, the expression level of G6PD is closely related to tumor progression and prognosis." (PMID 41328353, 2026). "We performed a comprehensive, cross-cohort analysis of BRAF, KRAS, and EGFR mutation subtypes using 64,807 cBioPortal tumor samples, 1570 cancer cell lines, and 2714 Belgian clinical cases." (PMID 42253180, 2026). "Our study aimed to investigate the role of platelets in transferring oncogenic KRAS to tumor cells and its subsequent impact on NSCLC progression and resistance to therapy." (PMID 40244100, 2025). "This selective internalization is attributed to the elevated levels of macropinocytosis in KRAS‐mutant tumor cells, a mechanism less prominent in stromal cells." (PMID 39951277, 2025). "ShRNA-mediated NRP1 knockdown in KRAS wildtype cells increased cell viability and tumor growth by decreasing the SMAD2 phosphorylation, whereas a KRAS mutant reverses the increased viability and leads to tumor inhibition." (PMID 40277760, 2025). "The transfer of KRAS-reactive TCR-engineered T cells that recognize multiple HLA-A*11:01+ tumors has been shown to significantly induce tumor regression in immunized HLA-A*11:01 transgenic mice." (PMID 41184283, 2025).
tumor (continued). "KRAS inhibition, tumor cell death, and therapeutic induction of senescence (via the SASP) have all been linked to immune remodeling." (PMID 40299790, 2025). "Taken together, these results demonstrate that USP25 is crucial for KRAS signaling and tumor growth." (PMID 40473213, 2025). "None of the analyzed variables (age, sex, histology, stage, EGFR, KRAS) were found to display a significant correlation with IDO-1 positivity in tumor and immune cells." (PMID 40475772, 2025). "GFH375 (VS-7375) demonstrated favorable oral bioavailability and potent efficacy in multiple KRAS G12D tumor models in preclinical studies." (PMID 40597785, 2025). "MiR-143 also exerts tumor-suppressive effects by targeting KRAS and ERK5, thereby reducing proliferation." (PMID 40943532, 2025). "The results indicated that extensive CpG hypomethylation in the NRAS and KRAS loci is essential for their overexpression in tumor cells." (PMID 39858030, 2025). "Mutations in the KRAS and GNAS oncogenes are common, but the reported frequencies vary greatly, most likely because of low tumor cellularity in peritoneal tumor samples." (PMID 41868810, 2025). "Dual inhibition impaired DDR2 and KRAS activity and induced robust apoptotic responses through mitochondrial pathways, leading to significant tumor growth inhibition in vivo." (PMID 39941857, 2025). "Yet none has crossed the threshold of demonstrable pathway shutdown in KRAS-addicted cell lines, let alone in vivo anti-tumour activity, because permeability and metabolic liability remain unresolved." (PMID 40872502, 2025). "The extensive range of these signals means that mutant KRAS impacts a variety of malignant phenotypes in tumor cells." (PMID 40611261, 2025). "Case in point, a recent translational CRC study demonstrated the power of integrating PDOs, OoC platforms, and PDX models to unravel KRAS-driven tumor biology." (PMID 40647462, 2025). "This study examined the impact of inflammation and genetic mutations on tumor development in a mouse model harboring APC, KRAS, or combined APC; KRAS mutations." (PMID 41285904, 2025). "In tumor cells, mutant KRAS primarily promotes immune evasion by activating the Raf-MEK-ERK signaling pathway, which regulates the expression of various immune factors and cell surface proteins." (PMID 40333779, 2025). "This reduction impairs miR-143-3p formation, activates the KRAS signaling pathway, and promotes tumor progression and oxaliplatin resistance." (PMID 41392287, 2025). "Their optimized PROTAC selectively degraded 13 of the 17 most common KRAS mutants, proving more effective than inhibition in driving tumor regression in experimental models." (PMID 40335986, 2025). "The significant associations between KRAS and BRAF mutations with tumor differentiation, grade, and metastatic patterns highlight their prognostic relevance." (PMID 40949797, 2025). "For instance, early‐stage EGFR mutant tumours display more complete epithelial characteristics compared with KRAS mutant tumours." (PMID 40847555, 2025). "KRAS G12C inhibitors can inhibit tumor growth by altering the metabolic state of tumor cells, particularly affecting the nucleotide synthesis pathway." (PMID 41200180, 2025). "RMC-9805 is a tricomplex KRAS G12D-ON inhibitor that demonstrated significant tumor regression in KRAS G12D-mutant solid tumors, including NSCLC xenograft models, and is now undergoing a phase I trial to better evaluate its safety and efficacy." (PMID 39941723, 2025). "We further show that USP25 inhibitors we have discovered are capable of destabilizing KRAS in cancer cells and are efficacious in blocking tumor xenograft growth in mice." (PMID 40473213, 2025).
tumor (continued). "Important discoveries often come from the bridging of distinct disciplines, as work by us and others at the intersection of KRAS biology and tumor immunology has started to reveal." (PMID 40662370, 2025). "The mutational profile of CRC tumors, including KRAS, NRAS, BRAF, PIK3CA, and AKT1 gene mutation and MSI status significantly influences the characteristics of the tumor microenvironment (TME) and directly impacts patient prognosis." (PMID 40724985, 2025). "Although several mouse models allow for regulated expression of mutant KRAS, selective isolation and analysis of transforming or tumor cells that produce the KRAS oncogene remains a challenge." (PMID 39786607, 2025). "RASON-KO inhibited KRAS downstream signaling, reduced in vitro proliferation and suppressed in vivo tumor growth in all three models." (PMID 40128846, 2025). "Compared with the control group, treatment with MYC/KRAS chimeric siRNAs significantly reduced tumor burden, with 6 mice showing complete tumor regression by day 10; however, resistance did develop in several tumors." (PMID 40762837, 2025). "We also assessed tumor cell–specific DPP4 and LKB1 protein levels using IHC in a panel of 57 patient-derived NSCLC samples, which were enriched for KRAS mutations." (PMID 41283988, 2025). "In preclinical studies, it effectively reduced ERK phosphorylation and inhibited KRAS-mutant tumor growth while sparing HRAS and NRAS." (PMID 41373672, 2025). "The differences are unreliable; however, there is a tendency towards a rarer detection of high-risk aberrations in patients with the KRAS, NRAS, and BRAF gene mutations at any tumor locus." (PMID 40943426, 2025). "There is a lack of high-volume data exploring the outcomes of patients with metastatic PDAC treated with cytotoxic regimens based on the tumor-specific KRAS permutations." (PMID 39777438, 2025). "In contrast, all 11 tumors from APC; KRAS mut mice were classified as Branched Type Tumor (P < 0.01)." (PMID 41285904, 2025). "We postulated that the KRAS mutant protein in CAFs is transferred either as a soluble entity or encapsulated within EVs derived from tumor cells." (PMID 39810420, 2025). "Active mutant KRAS drives critical signalling cascades for tumour growth, endocytosis and cytoskeletal organization." (PMID 39843398, 2025). "Association of the expressions of SRC, JUNB and FOSB as well as PD-L1 expression in tumor samples of KRAS-mutant NSCLC patients." (PMID 40599804, 2025). "The nanoparticle formulation demonstrated significant tumour targeting and sustained pharmacodynamic effects, effectively inhibiting the KRAS G12D downstream ERK signalling pathway." (PMID 41463025, 2025). "Chemokines are essential cytokines for infiltrating peripheral blood-derived monocytes into the interior of tumor tissues, and KRAS preferentially regulates macrophages through modulating chemokine secretion." (PMID 41184283, 2025). "The well-known impact of KRAS signaling on the tumor microenvironment (TME) and immune response has raised high expectations for ongoing combination trials with ICI." (PMID 40723270, 2025). "In a syngeneic colorectal KRAS mutant cancer model, tumor inhibition was superior when engrafted mice were first treated with MEKi followed by the addition of ICIs." (PMID 40486486, 2025). "MAPK and PI3K are probably STPs that drive tumor growth, given that more than 90% of PDAC tumors have KRAS mutations." (PMID 41373541, 2025). "From the WES of the patient’s original tumor, we identified the KRAS and PIK3CA driver genes, which were reported to be frequently observed in MLA." (PMID 41311737, 2025).